KIT (KIT proto-oncogene, receptor tyrosine kinase)
Diseases named in the same sentence as KIT in open-access papers (continued):
Sharing a sentence is not in itself a finding about the gene and the disease.
vulvar carcinoma (2 papers, 2012 to 2021). "Regarding treatment and further predictive values of c-KIT, the positive overexpression of this receptor was found to be associated with a better global and disease free survival in patients with vulvar cancer." (PMID 22839358, 2012). "c-KIT expression was scored by immunohistochemistry (IHC) as positive or negative in 139 formalin-fixed paraffin-embedded (FFPE) cases of vulvar carcinomas arrayed in a tissue microarray (TMA) using the DAKO® A4502 rabbit polyclonal c-KIT antibody (diluted 1:100)." (PMID 22839358, 2012). "In summary, novel conservative surgical approaches may be possible after IHC evaluation of c-KIT in vulvar cancer, bringing results from bench to the bedside in order to provide a better psychosocial quality of life for the women." (PMID 22839358, 2012). "For this reason, contrary to the situation found in other c-KIT positive tumors, the use of a c-KIT inhibitor such as Gleevec® may be inappropriate in vulvar cancer." (PMID 22839358, 2012). "Thus, molecular marker evaluation (c-KIT positivity), could be used as a prognostic factor for vulvar carcinoma, implementing translational research findings into part of a more personalized approach to each individual patient and their therapy." (PMID 22839358, 2012). "Thus, positivity of c-KIT as evaluated by IHC may be a good predictor for use of more conservative surgery techniques and lymph node dissection in vulvar cancer." (PMID 22839358, 2012). "Thus, c-KIT positivity could be used as a prognostic factor for vulvar carcinoma." (PMID 22839358, 2012). "This implies that the most aggressive vulvar cancer cases may not benefit from c-KIT targeted therapies as they already have low c-KIT expression." (PMID 22839358, 2012). "We assessed mRNA expression of c-KIT and its protein product in vulvar squamous cell carcinomas and correlated these data with clinicopathological features and with the presence of HPV infection, in order to determine the prognostic importance of this receptor in vulvar cancer." (PMID 22839358, 2012).
vulvar tumors (2 papers, 2012 to 2022). "Our findings indicate that those vulvar tumors staining positively for c-KIT present better prognosis." (PMID 22839358, 2012).
Achalasia (1 paper, 2021). A disorder of esophageal motility characterized by the inability of the lower esophageal sphincter to relax during swallowing and by inadequate or lacking peristalsis in the lower half of the body of the esophagus. "Another take-away lesson is that clinicians need to remember that more than one member of the same family with achalasia-like symptoms, mast cell or skin pigmentation disorders, or GISTs should be investigated for c-KIT mutation." (PMID 34064058, 2021).
albinism (1 paper, 2023). A congenital disorder characterized by partial or complete absence of melanin pigment in the eyes, hair, or skin. "This study aimed to identify single-nucleotide polymorphisms (SNPs) in the coding region of MC1R and exons 2 and 3 of KIT associated with coat color abnormalities (white-spotting and albinism) in Bali cattle using direct sequencing." (PMID 37577199, 2023). "Various genes, including ASIP (agouti), TYR (albinism), TYRP1 (brown), KIT (dominant white), KITLG (roan), PMEL (dilution), melanocortin 1 receptor (MC1R) (extension), and MITF (white-spotted), have been identified as important pigmentation genes underlying coat color variation." (PMID 37577199, 2023).
arrhythmogenic right ventricular cardiomyopathy (1 paper, 2021). "Silencing of c-KIT led to the down-regulation of several cardiomyopathic genes, especially of hypertrophic cardiomyopathy as well as of dilated and arrhythmogenic right ventricular cardiomyopathy, revealing a positive effect of c-KIT silencing on several disease entities." (PMID 33469076, 2021).
benign thyroid tumors (1 paper, 2015). "Conversely, KIT mRNA expression levels were significantly higher (P-value = 0.0006) in benign thyroid tumors (mean = 1.19) compared with malignant tumors (mean = 0.13)." (PMID 26581891, 2015). "We found that KIT mRNA expression levels were significantly higher in benign thyroid tumors compared with malignant ones, thereby confirming our previous results." (PMID 26581891, 2015).
bone sarcoma (1 paper, 2021). A sarcoma that arises from the bone. "Unfortunately, and despite international efforts, in bone sarcomas we could not identify any target such as KIT or EGFR through which to affect tumor biology in a significant way." (PMID 34831119, 2021).
bronchiolitis obliterans (1 paper, 2019). "A total of 60 BAL samples (20 with bronchiolitis obliterans (BOS), 20 with restrictive allograft syndrome (RAS), and 20 with stable allografts (STA)) were collected from 60 unique lung transplant patients; cfDNA and CXCL10 were measured by the ELISA-based KIT assay." (PMID 30781765, 2019).
bullous pemphigoid (1 paper, 2018). Bullous pemphigoid (BP) is the most common form of autoimmune bullous dermatosis. "Bullous pemphigoid patients also have anti-BP180 IgE autoantibodies, which are involved in tissue injury; therefore, a potential role of MCs in anti-BP180 IgE-induced BP should be determined in both KIT-dependent and KIT-independent MC-deficient strains." (PMID 29545809, 2018).
Burkitt lymphoma (1 paper, 2013). A rare form of malignant mature B-cell non-Hodgkin lymphoma. "Therefore, we first screened different CRC cell lines for c-KIT, FLT3 and MSCF expression in comparison to the Burkitt lymphoma cell line Daudi." (PMID 23900414, 2013).
cavernous hemangioma (1 paper, 2021). A hemangioma characterized by the presence of cavernous vascular spaces. "Should mutated-C KIT be expressed in Cavernous Hemangiomas of the brain and liver, the potential treatment effect could have a far great impact on modern medicine." (PMID 34439864, 2021). "In the present, study we have demonstrated the expression of c-KIT in orbital cavernous hemangiomas through immunohistochemical staining." (PMID 34439864, 2021). "Furthermore, investigation of the expression of C KIT in Cavernous Hemangioma of other specific anatomical locations such as brain or liver will need to be carried out." (PMID 34439864, 2021).
childhood cancers (1 paper, 2020). "Abnormalities in six genes (NRAS, ABL1, JAK2, KIT, ALK and BRAF) were common in childhood cancers as well as adult cancers, for which at least one approved drug could be a potentially actionable drug." (PMID 33051474, 2020).
chlamydial infection (1 paper, 2015). "The dose-dependent downregulation of mid phase-chlamydial infection by dasatinib, which can inhibit the activity of EphA2, Src, BCR-Abl, KIT and PDGFR, did not correlate well with the downregulation of the PI3K pathway." (PMID 25906164, 2015).
congenital heart disease (1 paper, 2023). A heart disease that is present at birth. "In the non-CRRT group, patients with advanced tumor (n = 3), congenital heart disease (n = 3), or the concentration of biomarkers exceeded the ELISA KIT detection range(n = 3) were excluded." (PMID 36650427, 2023).
diffuse intrinsic pontine glioma (1 paper, 2019). A neuroglial tumor that arises from the middle portion of the brain stem. "DNA analysis of a diffuse intrinsic pontine glioma (DIPG), TH02_0092_S01, revealed copy number gains of KDR (OMIM 191306), KIT (OMIM 164920), and PDGFRA, located on 4q12." (PMID 31651965, 2019).
encephalitis (1 paper, 2025). An acute inflammatory process affecting the brain parenchyma. "The resultsrevealed upregulation of the MET proto-oncogene receptor tyrosine kinase (MET)and KIT proto-oncogene receptor tyrosine kinase (KIT) in the encephalitis group,while interleukin 1 receptor type 2 (IL1R2) was downregulated compared to thenon-SAE group." (PMID 40985687, 2025). "Our results indicate that, comparedto the non-encephalitis group, the encephalitis group shows significant upregulationof immune-related genes MET and KIT, while IL1R2 is downregulated." (PMID 40985687, 2025). "Specifically, we identified six differentiallyexpressed immune genes—MET, KIT, IL1R2, MAFF, CD69, andCEBPD—between the encephalitis and non-encephalitis groups." (PMID 40985687, 2025).
endothelial dysfunction (1 paper, 2023). In vascular diseases, endothelial dysfunction is a systemic pathological state of the endothelium (the inner lining of blood vessels) and can be broadly defined as an imbalance between vasodilating and vasoconstricting substances produced by (or acting on) the endothelium. "The inhibition of the KIT and RAF1 pathways leads to vascular stem cell damage and endothelial dysfunction." (PMID 37692846, 2023).
esophageal motility disorder (1 paper, 2023). "This patient and his father had a germline mutation in exon 17 of the KIT gene and had also multiple GISTs and esophageal motility disorder." (PMID 37870660, 2023).
extracutaneous melanoma (1 paper, 2014). "Because mutations in c-KIT (and BRAF) are now being successfully exploited by new targeted therapies, it would appear appropriate to perform relevant mutation testing of primary extracutaneous melanoma in patients in whom systemic treatment is being considered." (PMID 24679002, 2014).
familial cancer (1 paper, 2021). "In contrast to numerous inactivating mutations in tumor suppressor genes, activating mutations contributing to familial cancer are rare and include the genes RET, MET, KIT, and ALK." (PMID 33916261, 2021).
fibromyxoma (1 paper, 2022). "As c-KIT and PDGFRA gene sequencing was not performed then, this specimen was thus diagnosed as gastric wall plexiform fibromyxoma based on its morphology." (PMID 35720122, 2022).
glaucoma (1 paper, 2020). Increased pressure in the eyeball due to obstruction of the outflow of aqueous humor. "Recently, it was found to decrease, together with its interaction partners CDH5 and KIT, in fibrotic versus non-fibrotic conjunctival fibroblast cell lines from patients with and without previous glaucoma surgery, respectively (their fig." (PMID 33047019, 2020).
Globozoospermia (1 paper, 2019). Any structural anomaly of the acrosome resulting in a round sperm head. "The result of this study clearly demonstrated that spermtr-KIT has an important association with fertilization inhumans, and its expression is decreased in individualswith low fertilization rate and globozoospermia." (PMID 31210438, 2019).
goiter (1 paper, 2012). Enlargement of the thyroid gland usually caused by lack of iodine in the diet, hyperthyroidism, or thyroid nodules. "In this analysis c-KIT resulted heterogeneously expressed in goiters, whereas PTC were negative." (PMID 22233760, 2012).
hand (1 paper, 2020). "Subungual tumors were significantly amplified in the regions 15q26.3 and the region on chromosome 4 including KIT whereas non-subungual foot/hand tumors were not." (PMID 33067454, 2020).
hemorrhage (1 paper, 2025). Loss of blood from the vascular compartment to the exterior or into nonvascular body space as a result of rupture or severance of the blood vessels. "Imatinib is also associated with conjunctival hemorrhages in ~2–11% of patients, thought to result from inhibition of c-KIT on conjunctival mast cells." (PMID 41568391, 2025).
Hepatic failure (1 paper, 2013). "In hepatic stellate cells, KITLG expression stimulated by IGF1R signaling may facilitate the KIT-dependent recruitment of inflammatory cells in injury and fibrosis and progenitor cells in hepatic failure, and may thus be associated with both disease progression and tissue regeneration." (PMID 24116170, 2013).
Histiocytosis (1 paper, 2020). An excessive number of histiocytes (tissue macrophages). "We found seven KIT mutations in the five mutant histiocytosis cases." (PMID 32372223, 2020).
hypertrophic cardiomyopathy (1 paper, 2021). A condition in which the myocardium is hypertrophied without an obvious cause. "Here, we identified serum protein c-KIT as a potential biomarker for HCM distinguishing between patients with hypertrophic cardiomyopathy and healthy subjects." (PMID 33469076, 2021). "The present study identified c-KIT as a novel protein biomarker for patients with hypertrophic cardiomyopathy and revealed a novel role for c-KIT to be directly involved in cardiac remodeling processes in HCM patients." (PMID 33469076, 2021).
Hypoalbuminemia (1 paper, 2022). The concentration of albumin in the blood circulation is below the lower limit of normal. "Further significant correlations were identified upon the KIT D816V allele burden in peripheral blood (r = 0.6, R2 = 0.4, P = 0.016) and hypoalbuminemia (r = − 0.5, R2 = 0.3, P = 0.041)." (PMID 35987779, 2022).
intestinal tumors (1 paper, 2020). "Poorly infiltrated GISTs, primarily KIT/PDGFRA WT intestinal tumors, showed activation of Hedgehog and WNT/β-catenin immune excluding pathways." (PMID 33048845, 2020).
ischemic colitis (1 paper, 2019). Inflammation of the colon due to colonic ischemia resulting from alterations in systemic circulation or local vasculature. "VEGFR inhibition was reported to be associated with ischemia and hypoxia in the bowel mucosa and to follow a pathogenesis similar to that of ischemic colitis by inhibition of c-KIT as well as imatinib." (PMID 31427707, 2019).
Kidney Cyst (1 paper, 2025). Abnormal fluid filled sac within the kidney, either acquired or congenital. "We propose that c-KIT is a crucial mediator of TSC renal cystogenesis and that its inhibition may constitute a novel approach for the treatment of kidney cysts in TSC." (PMID 41429944, 2025).
lacrimal gland disease (1 paper, 2025). "Avapritinib showed a particularly prominent specificity for lacrimal gland disease, which may be related to the role of KIT/PDGFRA inhibition in the lacrimal secretion pathway." (PMID 40951360, 2025).
lymphoid leukemia (1 paper, 2018). A malignant lymphocytic neoplasm of B-cell or T-cell lineage involving primarily the bone marrow and the peripheral blood. "In keeping with a role for IRX3 in promoting the development of lymphoid leukemias, we found that irradiated congenic mice transplanted with IRX3-expressing KIT+ BM HSPCs developed lymphoid leukemias with incomplete penetrance." (PMID 29346763, 2018).
mastitis (1 paper, 2016). Inflammation of breast tissue during lactation or postpartum due to an obstructed duct or infection. "A total of 28 genes (e.g., CXCL14, KIT, and SLC4A11) were suggested as the most promising candidates associated with S. aureus-induced mastitis for follow-up functional studies." (PMID 28083515, 2016). "Integrated analysis with QTL database further suggested 28 genes (e.g., CXCL14, KIT, and SLC4A11) as candidates of bovine mastitis." (PMID 28083515, 2016).
megacolon (1 paper, 2014). "In this study we analysed the English spotting coat color locus in Checkered Giant rabbits associated with a pathological state that could be a natural genetic model of megacolon, and showed that this phenotype is caused by mutational event(s) affecting the KIT gene." (PMID 24736498, 2014). "The present findings can help understand the neuro-muscular changes occurring in human non-aganglionic megacolon, though additional studies will be needed to better characterize the mutational event in KIT and the specific role of ENS in this restrictive condition." (PMID 24736498, 2014). "Although we could not identify the causative variant in the rabbit KIT gene responsible for the spotted phenotype, expression analyses in colon and cecum support the role of this gene in determining the associated megacolon defect of the English spotting locus in Checkered Giant rabbits." (PMID 24736498, 2014). "These KIT gene expression results can establish a link between this coat color locus and altered functionality of the ICC, that may be involved in determining the megacolon defect in En/En rabbits." (PMID 24736498, 2014).
memory impairment (1 paper, 2021). "In this study, to investigate the mechanisms underlying the effects of KIT on stress-induced brain dysfunctions such as a depressed state and memory impairment, we examined whether KIT prevents behavioral and neurophysiological abnormalities in mice treated chronically with corticosterone (CORT)." (PMID 34765515, 2021). "In contrast, the preventive effects of KIT on CORT-induced memory impairment or reduced hippocampal cell survival and number of hippocampal new-born immature neurons seem to be caused by another component." (PMID 34765515, 2021). "In conclusion, this study suggests that KIT may ameliorate a stress-induced depressed state and memory impairment via prevention of adverse effects of stress on hippocampal cell survival, the number of new-born hippocampal immature neurons, accumbal dendritic spines and accumbal GDNF levels." (PMID 34765515, 2021).
multinodular goiter (1 paper, 2015). Nodular goiter characterized by more than one discrete tissue mass. "Separate analysis of a subset of the multinodular goiter samples with more aggressive PTC subtypes revealed 2 - 4-fold upregulation in the levels of CHEK1, c-MET and TIMP1, and a 2-4-fold downregulation of BCL2, c-KIT, TG and PPARγ (lower part)." (PMID 25868389, 2015).
Myoepithelial carcinoma (1 paper, 2024). "Myoepithelial carcinoma (MYOC) was positive for BMI1 while showing scarce positivity for c-KIT." (PMID 39858584, 2024).
ocular melanoma (1 paper, 2021). A melanoma that arises from the structures of the eye or ocular adnexa. "It was later proven that KIT mutations occur in ocular melanomas at a frequency of 11%, with a limited correlation of KIT-positivity with mutational status." (PMID 34639089, 2021).
oculocutaneous albinism (1 paper, 2015). Oculocutaneous albinism (OCA) describes a group of inherited disorders of melanin biosynthesis characterized by a generalized reduction in pigmentation of hair, skin and eyes and variable ocular findings including nystagmus, reduced visual acuity and photophobia. "Among the four genes under-expressed in Duroc, two genes are specifically known to be involved in skin coloration: KIT (v-kit Hardy-Zuckerman 4 feline sarcoma viral oncogene homolog or Dominant white locus in pigs;) and OCA2 (oculocutaneous albinism II)." (PMID 26651482, 2015).
oral submucous fibrosis (1 paper, 2023). "A study that compared mast cell densities using c-KIT and toluidine blue stains confirmed that c-KIT is more accurate in determining mast cell density in oral submucous fibrosis." (PMID 37928785, 2023).
ovarian carcinosarcoma (1 paper, 2012). A highly aggressive malignant neoplasm arising from the ovary. "One patient with ovarian carcinosarcoma had a KIT P585P mutation detected in FFPE, but not in cpDNA." (PMID 23144797, 2012).
ovarian small cell carcinoma (1 paper, 2007). A carcinoma that arises from the ovary and is characterized by the presence of small malignant cells. "We examined in situ expression of stem cell-related (NANOG, OCT-3/4, KIT, AP-2γ) and germ cell-specific proteins (MAGE-A4, NY-ESO-1, TSPY) using a tissue microarray consisting of 60 OGCT tissue samples and eight ovarian small cell carcinoma samples." (PMID 17274819, 2007).
Pruritus (1 paper, 2025). Pruritus is an itch or a sensation that makes a person want to scratch. "Additionally, pruritus was significantly more common in KIT p.D816V-positive individuals, suggesting that the KIT mutation may affect MC activation symptoms in CM children." (PMID 40649802, 2025). "Further, pruritus was significantly more common in KIT p.D816V + patients compared to KIT p.D816V individuals (57.1% versus 9.8%; p = 0.03)." (PMID 40649802, 2025).